IL22 (interleukin 22)
Diseases named in the same sentence as IL22 in open-access papers (continued):
Sharing a sentence is not in itself a finding about the gene and the disease.
psoriasis (continued). "Therefore, IL-22 is considered to contribute to the acanthosis in psoriasis and lichenification in AD." (PMID 37881433, 2023). "Moreover, a large pool of TRM cells express IL-17A alone, IL-17A and IL-22, or IL-22 alone, and persist in post-lesional psoriasis skin." (PMID 36901778, 2023). "Furthermore, we provide evidence that the expression of uc.291, FLG and LOR is reduced, while ACTL6A mRNA is up-regulated, in an in vitro psoriasis-like model obtained by treating differentiated keratinocytes with interleukin 22 (IL-22)." (PMID 38041107, 2023). "Previous studies supported the finding of the importance of the IL17/IL22/IL23 axis in the pathogenesis of psoriasis, where IL23 is reported not only to support the Th17 lymphocyte producing IL-17, but also stimulate IL-17 production via innate T lymphocyte such as Gamma delta T lymphocytes (Tγδ)." (PMID 37010718, 2023). "This also indicates that serum IL-22 is a potential predictor for the severity of psoriasis." (PMID 38008779, 2023). "Furthermore, we used a psoriasis-associated cytokine mixture (Pso Mix) (IL-17, TNF-α, IL-1α, OSM and IL-22) to stimulate primary KCs to mimic the psoriatic profile." (PMID 37497003, 2023). "Factors such as IL-17 and IL-22 contribute to the over proliferation and differentiation of KCs, leading to the abnormal proliferation of epidermal cells and the formation of scaly lesions characteristic of psoriasis." (PMID 38239345, 2023). "Furthermore, curcumin minimizes the damage caused by psoriasis, as it significantly inhibits STAT3 phosphorylation induced with IL-22, achieving a reduction of 95.6%, and exhibits a 47% inhibition of IL-22 and IL-18." (PMID 37896042, 2023). "Furthermore, Hashimoto and colleagues have detected a decrease in the mRNA expression levels of IL-22, IL-23 and IL-33 in a mouse model of psoriasis." (PMID 37631238, 2023). "Dermal injection of psoriasis biomarker IL-23 directly into mice results in the development of skin inflammation driven by Th17 cells (the same as in human psoriasis) and upregulation of pro-inflammation cytokines (IL-22, IL-17A, INF-γ)." (PMID 37298466, 2023). "Ligilactobacillus and Anaeroplasma (inhibited in CUR mice) were positively correlated with multiple psoriasis‐related factors, such as IL‐6, IL‐17A, IL‐22, IL‐23, while Rikenella, Alistipes, and Mucispirillum (promoted in CUR mice) were negatively correlated with them." (PMID 37647442, 2023). "In a recently published article, the authors indicate that oestrogen has a dual potential in the pathogenesis of psoriasis, including suppression of inflammation by enhancing IL-10 production and the enhancement of inflammation by induction of IL-22 and IL-23 expression." (PMID 38139164, 2023). "Furthermore, psoriasis-related factors, such as IL-17A, IL-17F, IL-22, and IL-23R, can be transcriptionally activated by STAT3, suggesting that STAT3 plays a promoting role in psoriasis development." (PMID 36835162, 2023). "To support our hypothesis on the involvement of uc.291 and its competitor ACTL6A in modulating keratinocyte differentiation, we decided to establish an in vitro model of psoriasis by treating differentiated cells with IL-22." (PMID 38041107, 2023). "In mouse psoriasis models, Nrf2 was reported to translocate to the nucleus in response to inflammatory cytokines such as IL-17 and IL-22, and upregulate the expression of key keratin genes in lesional epidermis, ultimately leading to keratinocyte proliferation." (PMID 37805522, 2023). "Th1 has been implicated in psoriasis, although evidence suggests that Th17 expression could be more important in psoriasis, producing various proinflammatory factors including IL-17 and IL-22." (PMID 38067173, 2023). "Under the condition of abundant IL-23 in psoriasis lesional skin, some macrophages may produce IL-17A, IL-22 and IFN-γ in addition to TNF-α as described in our previous review article." (PMID 38022549, 2023).
psoriasis (continued). "Considering the forementioned findings, the IL17/IL22/IL23 axis could be considered a reliable biomarker for monitoring psoriasis progression and treatment efficacy." (PMID 37010718, 2023). "Finally, we used an in vitro model of psoriasis in which human differentiated keratinocytes are treated with interleukin 22 (IL-22)." (PMID 38041107, 2023). "In addition, T cells expressed IL17A, IL17F, and IL22 that, coupled with their receptors expressed by myeloid cells and keratinocytes, are known to promote inflammation in psoriasis." (PMID 37308489, 2023). "Furthermore, the induction of IL-22 and the involvement of the IL-40 family are crucial in the pathogenesis of psoriasis." (PMID 38239345, 2023). "However, IL-22 is still responsible for upregulating psoriasis mostly by collaborating with other immune components." (PMID 35203707, 2022). "Of relevance to the present study, recent data indicated that in patients with psoriasis IL-17 and IL-22 producing cells are in a substantial proportion CD3- innate lymphoid cells (ILC), and adalimumab treatment decreased the percentages of circulating NKp44+ILC3." (PMID 35925616, 2022). "Nonetheless, psoriasis is, indeed, caused by the chaos of triggered immune cells and its cytokines, such as tumor necrosis factor (TNF)-α, interleukin (IL)-17, IL-22, IL-23, and granulocyte–macrophage colony-stimulating factor (GM-CFS) that flare up throughout the pathway." (PMID 35203707, 2022). "Also, the pathological pattern of psoriasis can be viewed as an uncontrolled IL-22 physiological activity in all aspects." (PMID 35911703, 2022). "Moreover, a large pool of α/β TRM cells expressing IL-17A alone, IL-17A and IL-22, or IL-22 alone persist in post-lesional psoriasis skin." (PMID 36361639, 2022). "As IL-22 proved beneficial effects in metabolic syndromes, anti-IL-22 treatment might deteriorate metabolic changes in psoriasis patients." (PMID 35911703, 2022). "We posited the low anti-IL-22 antibodies might contribute to the development of psoriasis due to failure of reducing excessive production of this cytokine." (PMID 36118416, 2022). "However, the emergence of IL-22-producing innate immune cells increase the complexity of immune activity in psoriasis." (PMID 35911703, 2022). "However, tapinarof (AHR agonist) increased the production of IL-22 in keratinocytes in vitro, while inhibited IL-22 in psoriasis mouse model." (PMID 35911703, 2022). "Interestingly, studies in synovial fluid from patients with PsA have shown increased CD4+/IL-17+ T-lymphocytes and decreased CD4+/IL-22+ T-lymphocyte, suggesting their different role in the pathogenesis of PsA vs. psoriasis." (PMID 35722498, 2022). "Notably, psoriasis is mediated by T-cell effector cytokines, including IL-17A, IL-22, and TNF-α, which induce antimicrobial peptides in keratinocytes and neutrophils." (PMID 36232814, 2022). "In addition, the IL-22-related signaling pathways PGE2/IL22/IL17 and IL-17/IL-22 are receiving increasing attention in eczema, psoriasis, and chronic obstructive pulmonary disease." (PMID 35432360, 2022). "In addition, SPRR2C, a potential regulator that modulates IL-22 stimulation, was upregulated in both atopic dermatitis and psoriasis lesional skin and was also downstream of the IL-17A and IL-17 + TNF signaling in keratinocytes." (PMID 35559048, 2022). "IL-22 exerts a pro-inflammatory action in both psoriasis and AD." (PMID 36359220, 2022). "The Th1 (TNF-α) and Th17 (IL-17A and IL-22)-related cytokines are important proinflammatory cytokines, involved in maintenance of chronic inflammatory response and epithelial tissues remodeling in psoriasis pathogenesis." (PMID 36741386, 2022). "However, lower serum IL-22 was detected in psoriasis patients with metabolic syndromes than that in patients without systemic complications." (PMID 35911703, 2022).
psoriasis (continued). "Psoriasis is defined as Th17-mediated disease, but results of a growing number of studies indicate the central role of IL-23 in the development of psoriasis due to its effects on sustention of cytotoxic Th17 cells and production of IL-17 and IL-22." (PMID 35313642, 2022). "Furthermore, serum IL-22 level was higher in psoriasis patients compared with healthy individuals and was also positively correlated with disease severity." (PMID 35563374, 2022). "IL-17A and IL-22 are produced by Th-17 cells and elevated levels of these cytokines are thought to be involved in the development and pathogenesis of autoimmune diseases, including psoriasis." (PMID 35337918, 2022). "Th17‐expressed IL‐22, which mediates IL‐23‐induced acanthosis and dermal inflammation in psoriasis, is also expressed by cells within the αβT/ILC cluster and may also contribute to IR‐induced keratinocyte hyperplasia." (PMID 35785521, 2022). "Neutralization of IL-22 prevents the development of psoriasis-like inflammation in mice." (PMID 36118416, 2022). "Interestingly, IL-22 is highly produced by activated mast cells within the plaque lesions of psoriasis and AD." (PMID 36314037, 2022). "Among them, type 3 ILCs (ILC3s) play a central role in the etiology and disease severity of psoriasis, which was ascribed to the elevated number of IL-22- and IL-17 A/F-producing ILC3s induced by their expression of RORγt transcription factors in psoriatic skin and blood." (PMID 36242051, 2022). "The results demonstrated that the mRNA levels of psoriasis-related cytokines, namely, IL-22 and IL-23, were significantly decreased in the group treated with 5 mg of pinocembrin compared with the vehicle-treated group (F-value = 101 and p = 0.0209 for IL-22; F-value = 1.83 and p = 0.0338 for IL-23)." (PMID 35116069, 2022). "In this study, we used HaCaT keratinocytes stimulated with M5, a cocktail of five inflammatory cytokines (TNF-α, oncostatin M, IL-1α, IL-17A, and IL-22), as an in vitro model of psoriasis with typical upregulation in the production of cytokines, chemokines, and antimicrobial peptides." (PMID 36555642, 2022). "Finally, Th17 and Th22 cells, along with their cytokines IL-17 and IL-22, contribute to a neutrophil migration and wound-healing-like pattern, such as psoriasis." (PMID 35911703, 2022). "Furthermore, curcumin intervention in T cells obtained from a mouse model of psoriasis showed that 10 μM curcumin concentration significantly blocked the secretion of IL-17, IL-22, IFN-γ, IL-2, IL-8 and TNF-α." (PMID 35979355, 2022). "IL‐22 has an important role in host defense and antimicrobial protection, however, when overexpressed it contributes to keratinocyte parakeratosis, acanthosis, and papillomatosis, which are hallmarks of psoriasis." (PMID 34913478, 2022). "Furthermore, Jeon and colleagues showed that elevating S1P by inhibiting of S1P lyase ameliorated IMQ-induced psoriasis-like dermatitis, and reduced IL-17- and IL-22-induced cell proliferation and promoted keratinocyte differentiation." (PMID 35075118, 2022). "Furthermore, the down-regulation of mRNA levels of psoriasis-related pro-inflammatory cytokines, such as IL-17, interleukin 22 (IL-22), IL-23, interferon-α (IFN-α), and Interferon-γ (IFN-γ) was observed with the treatment of PO." (PMID 35566346, 2022). "Furthermore, it was shown that IL-17 and IL-22 enhance the proliferation of psoriasis-related keratins via Nrf2 signaling." (PMID 35313642, 2022). "IL-6 and/or IL-22 have pro-inflammatory activities toward lymphoid and myeloid lineage immune cells, and keratinocytes, which along with other cytokines drive their proliferation, differentiation and acute phase response observed in psoriasis." (PMID 36741386, 2022). "Th17 cells produce cytokines such as IL-21, IL-17, and IL-22 to accelerate psoriasis symptoms." (PMID 35409158, 2022). "The axis formed by IL-23/IL-17/IL-22 was thought to be the trigger of psoriasis." (PMID 34884834, 2021).
psoriasis (continued). "Moreover, psoriasis has been associated with increased inflammatory cytokines, in which the IL-23/Th17 axis with TNF-α, IL-21, and IL-22 play a role in the control of inflammation." (PMID 34722590, 2021). "Th17 cells produce IL-17A and IL-22, which are the main cytokines in the pathogenesis of psoriasis." (PMID 33483537, 2021). "In a study of patients with psoriasis, it is found that IL-21 up-regulates RORγt expression and down-regulates the expression of Foxp3, increases secretion of IL-17A and IL-22, and finally induces T-helper 17 (Th17) and Tregs imbalance and promotes inflammation in psoriasis." (PMID 34490267, 2021). "IL-22 contributes to psoriasis pathogenesis, but may also play a role in other inflammatory skin diseases, such as atopic dermatitis." (PMID 34868019, 2021). "In addition, IL-23 promoted the expression of IL-17A, IL-17F, IFN-γ, and IL-22 in M0 macrophages, and IL-23-treated M0 macrophages significantly enhanced psoriasis-like dermatitis in the mouse model." (PMID 33681365, 2021). "To investigate the specific effects of SPRR2C, we stimulated human immortalized keratinocytes (HaCaT cells) with IL-22 (100 ng/ml) for 24 h to mimic the in vitro pathological changes in psoriasis, conducted SPRR2C knockdown in HaCaT cells, and then examined related indexes." (PMID 33452236, 2021). "Indeed, it was reported that the numbers and frequency of IL-22+ RORγt+ CD56+ ILC3s were remarkably higher in the skin from psoriasis patients relative to healthy skin." (PMID 34831296, 2021). "In addition to IL-22’s pleiotropic functions, IL-22-deficient mice were shown to be almost protected from imiquimod (IMQ)-induced psoriasis, proving the key role of IL-22 in the pathogenesis of psoriasis." (PMID 34685526, 2021). "IL-22 is a critical cytokine in the modulation of tissue responses during inflammation and is highly upregulated in many chronic inflammatory disease patients, including those with psoriasis, rheumatoid arthritis, and inflammatory bowel disease (IBD)." (PMID 34868019, 2021). "Collectively, these findings suggest that IL-17- and IL-22-producing ILC3s could directly contribute to the pathogenesis of psoriasis." (PMID 34831296, 2021). "In addition, IL-22 neutralizing antibody treatment decreased antimicrobial peptide levels and inhibited disease development in a psoriasis mice model, suggesting the therapeutic potential of IL-22 inhibitors in psoriasis." (PMID 34295334, 2021). "Especially IL-17A and TNF-α display an important inflammatory effect in the pathogenesis of psoriasis, whereas only IL-22, but not IL-17A and TNF-α, cause epidermal alterations typical for psoriasis such as acanthosis." (PMID 33801280, 2021). "Both IL-17 and IL-22 are known to play an important role in the pathogenesis of psoriasis." (PMID 34769769, 2021). "However, the use of RILES technology allowed us to underline the functional activity of miR-21-3p in KCs in response to IL-22 stimulation, consequently putting this cytokine at the center of psoriasis immunopathology and miRNA modulation." (PMID 34685526, 2021). "This study involved an exploration of the effects of FZHFZY on epidermal differentiation and its underlying mechanisms in interleukin (IL)-17A/IL-22/interferon (IFN)-γ/tumour necrosis factor (TNF)-α–stimulated HaCaT cells and in a mouse model of imiquimod (IMQ)-induced psoriasis." (PMID 34456715, 2021). "Furthermore, CD8+ T cells producing IL-17 and CD4+ T cells producing IL-22 remain in resolved lesions and can be stimulated to produce psoriasis-related cytokines even after treatment with biologics such as infliximab for several years." (PMID 34445713, 2021). "Therefore, our in vitro psoriasis model using primary keratinocytes isolated from the skin of healthy donors treated with a combination of IL-17A, IL-22 and TNF-α provides an interesting substitute model that has already proven its capability." (PMID 34641358, 2021).
psoriasis (continued). "The topical application of a natural compound mixture (PSM) of herbs, containing emodin, genipin, chlorogenic acid, cimigenoside, and ginsenoside Rb1, alleviated IMQ-induced psoriasis-like dermatitis and reduced the proliferation rate of IL-22-stimulated keratinocytes." (PMID 33935720, 2021). "In line with our hypothesis that miR-21-3p and the IL-22 axis play essential roles in psoriasis, we performed RNA-seq analysis in miR-21-3p-overexpressing KCs to gain deeper insights into the transcriptome." (PMID 34685526, 2021). "In contrast, neutralizing Abs to IL-22 are being investigated for treatment of psoriasis." (PMID 34868019, 2021). "Consequently, exposure of keratinocytes to the IFN-γ/IL-17A/IL-22 cytokine combination represents a reliable psoriasis-like in vitro model." (PMID 33986690, 2021). "Th17 cells, as well as Th1 cells and keratinocytes, secrete TNF-α, IFN-γ, IL-1β, IL-6, IL-12, IL-17A, IL-22, IL-23 participating in pathophysiologic processes of psoriasis and current biological therapies as T cell-directed agents have demonstrated excellent efficacy in psoriasis." (PMID 33685393, 2021). "DNA methylation profiles can be used to stratify psoriasis patients by clinical features, including age of disease onset and IL-22 copy number variation, allowing the potential future use of epigenomics in classifying psoriasis patients for diagnostic or treatment purposes." (PMID 34639182, 2021). "This action has also been demonstrated using a psoriasis gene panel in human keratinocytes in which LUT7-G showed the ability to neutralize the inflammation psoriatic process induced by IL-22, thus demonstrating a wide anti-inflammatory activity, mostly independent from the cell type model used." (PMID 33525692, 2021). "Here, we established psoriasis cell model through stimulating keratinocytes HaCaT with IL-22." (PMID 33393621, 2021). "At each step of the psoriasis molecular pathway, different inflammatory cytokines such as IL-6, IL-17, IL-22, and IL-23 are triggered, on the other side, growth factors such as EGF, VEGF, KGF, and IGF-1, which underscores the central role which predominantly drives epidermal hyperplasia." (PMID 33849555, 2021). "To assess the function of PI3Kδ in psoriasis skin, we evaluated the effects of a potent, ATP-competitive, and selective PI3Kδ inhibitor—seletalisib—on the key intracellular pathways known to be activated by IL-22 or TNF-α in human keratinocytes." (PMID 34685616, 2021). "In addition, the mRNA expression of the IL-22/IL-22BP ratio increased 227-fold in lesions of psoriasis vs. HC (P < 0.05)." (PMID 32632545, 2020). "Correlations between IL-22/IL-22R1 levels and the thickness of psoriatic lesions suggested that IL-22 might positively regulate abnormal hyperplasia in psoriasis." (PMID 32632545, 2020). "As the role of IL-17 and IL-22 in psoriasis became apparent, hypotheses about dual secreting T cell phenotypes emerged." (PMID 31973112, 2020). "Altogether, these results suggested that IL-22 might participate in developing abnormal hyperplasia in psoriasis." (PMID 32632545, 2020). "IL-22 can induce hyperproliferation, cell migration, and disrupt the terminal differentiation of keratinocytes, resulting in pathological epidermal hyperplasia in psoriasis." (PMID 33149756, 2020). "The ozone therapy effectively reduced the up‐regulation of IL‐17 and IL‐22 in psoriasis lesions." (PMID 32168425, 2020). "IL-17, IL-22, and IL-23 are known to play important roles in the pathogenesis of psoriasis, and NK cells could produce both IL-17 and IL-22." (PMID 32917058, 2020). "It is reported that IL-22 is involved in the development and pathogenesis of several autoimmune diseases such as systemic lupus erythematosus, rheumatoid arthritis, multiple sclerosis, sjögren syndrome, and psoriasis." (PMID 33344684, 2020). "In addition, Th17 cells and Th17-related cytokines, such as interleukin (IL)-17A, IL-22, and IL-23, are involved in the pathogenesis of psoriasis." (PMID 32316255, 2020).